UBXN2B (UBX domain protein 2B)
Description:
Adapter protein required for Golgi and endoplasmic reticulum biogenesis. Involved in Golgi and endoplasmic reticulum maintenance during interphase and in their reassembly at the end of mitosis. The complex formed with VCP has membrane fusion activity; membrane fusion activity requires USO1-GOLGA2 tethering and BET1L. VCPIP1 is also required, but not its deubiquitinating activity. Together with NSFL1C/p47, regulates the centrosomal levels of kinase AURKA/Aurora A during mitotic progression by promoting AURKA removal from centrosomes in prophase. Also, regulates spindle orientation during mitosis.
Synonyms: p37
Tractability: PROTAC: ubiquitination databases record sites on it; its protein half-life has been measured.
Gene: Protein-coding gene on chromosome 8 (58,411,349 to 58,452,164, forward strand). Ensembl gene ENSG00000215114.
Subcellular location: Nucleus; Cytoplasm, cytosol; Endoplasmic reticulum; Golgi apparatus; Cytoplasm, cytoskeleton, microtubule organizing center, centrosome
Subcellular location (Human Protein Atlas): Nucleoplasm
Gene Ontology:
Molecular function: protein binding; ubiquitin binding
Biological process: establishment of mitotic spindle orientation; negative regulation of protein localization to centrosome; positive regulation of mitotic centrosome separation; protein unfolding; autophagosome assembly; Golgi organization; membrane fusion; nuclear membrane reassembly; proteasome-mediated ubiquitin-dependent protein catabolic process
Cellular component: ATPase complex; cytosol; nucleus; centrosome; endoplasmic reticulum; Golgi apparatus; spindle pole centrosome
Genetic constraint (gnomAD): Loss-of-function variants: 15 observed, 23.45 expected, observed/expected ratio (o/e) 0.64, 90% interval 0.43 to 0.99. The upper end of that interval is the gene's LOEUF score, 0.99, which puts it in group 4 of 6, group 1 being the genes least tolerant of losing a copy. Missense variants: 325 observed, 322.04 expected, observed/expected ratio (o/e) 1.01, 90% interval 0.92 to 1.11. Synonymous variants: 132 observed, 121.64 expected, observed/expected ratio (o/e) 1.09, 90% interval 0.94 to 1.25.
Homologues: Orthologues: chimpanzee UBXN2B (100% identical), macaque UBXN2B (98% identical), dog UBXN2B (95% identical), pig UBXN2B (92% identical), rat Ubxn2b (89% identical), guinea pig UBXN2B (89% identical), mouse Ubxn2b (85% identical), rabbit UBXN2B (80% identical), tropical clawed frog ubxn2b (64% identical), Drosophila melanogaster p47 (33% identical), Drosophila melanogaster CG42383 (28% identical), Caenorhabditis elegans ubxn-2 (24% identical). Paralogues in human: NSFL1C (52% identical), UBXN2A (26% identical), UBXN11 (19% identical).
Diseases named in the same sentence as UBXN2B in open-access papers:
UBXN2B is named in the same sentence as 3 diseases in open-access papers, as found by Europe PMC text mining. Sharing a sentence is not in itself a finding about the gene and the disease. The quoted sentences say what the papers report.
gall bladder diseases (1 paper, 2020). "The other exclusive vQTL (rs1030431) is 12,126 bp upstream from UBXN2B; the SNP is significantly associated with gall bladder diseases and lipid metabolism traits in the UKB34." (PMID 32242144, 2020).
tumour (1 paper, 2024). "However, it remains unknown whether the remaining members of the UBXD family, such as UBXN4, UBXN11, and UBXN2B, have effects on tumour formation and progression in vitro and in vivo." (PMID 38365777, 2024).
UBXN2B also shares sentences with these, for which no sentence is quoted: cholelithiasis (1 paper).